ZMYM3 (zinc finger MYM-type containing 3)
Description:
Required for regulation of cell morphology and cytoskeletal organization.
Synonyms: DXS6673E; KIAA0385; ZNF261; ZNF198L2; MYM; XFIM; XLID112
Tractability: PROTAC: UniProt records ubiquitination sites on it; ubiquitination databases record sites on it; its protein half-life has been measured.
Gene: Protein-coding gene on chromosome X (71,239,617 to 71,255,269, reverse strand). Ensembl gene ENSG00000147130.
Subcellular location: Nucleus
Subcellular location (Human Protein Atlas): Nucleoplasm
Gene Ontology:
Molecular function: protein binding; DNA binding; zinc ion binding
Cellular component: nucleoplasm; nucleus
Homologues: Orthologues: macaque ZMYM3 (100% identical), chimpanzee ZMYM3 (99% identical), pig ZMYM3 (99% identical), rabbit ZMYM3 (99% identical), dog ZMYM3 (98% identical), guinea pig ZMYM3 (97% identical), rat Zmym3 (96% identical), mouse Zmym3 (95% identical), tropical clawed frog zmym3 (65% identical). Paralogues in human: ZMYM2 (39% identical), ZMYM4 (35% identical), ZMYM6 (20% identical), ZMYM1 (15% identical), QRICH1 (15% identical), ZMYM5 (12% identical), GTF2IRD1 (8% identical), KIAA1958 (6% identical), THAP12 (6% identical), GTF2I (5% identical), SCAND3 (5% identical), ZBED11 (5% identical), and 6 more.
Diseases named in the same sentence as ZMYM3 in open-access papers:
ZMYM3 is named in the same sentence as 27 diseases in open-access papers, as found by Europe PMC text mining. Sharing a sentence is not in itself a finding about the gene and the disease. The quoted sentences say what the papers report.
mental retardation (5 papers, 2011 to 2023). "Mutations of ZMYM3 has been implicated in mental retardation, and all six ZMYM-family transcription factors are widely expressed in human tissues." (PMID 37395395, 2023). "We report in this study that Zmym3, a gene that initially came to people’s attention for its potential roles in X-linked mental retardation and epigenetic regulation, has an essential role in mouse spermatogenesis." (PMID 28661483, 2017). "The other genes are potassium channel tetramerization domain containing 1 (KCTD1), zinc finger, myeloproliferative and mental retardation type 2 (ZMYM2)/zinc finger protein 198 (ZNF198), ZMYM3/ZNF261, ZMYM4/ZNF262 and glutamine-rich protein 1 (QRICH1)." (PMID 22011512, 2011).
medulloblastoma (4 papers, 2014 to 2023). A malignant, invasive embryonal neoplasm arising from the cerebellum. "Recurrent loss of function mutations of ZMYM3 have been identified in several cancers including chronic lymphocytic leukemia, medulloblastoma, Ewing sarcoma and pediatric cancers." (PMID 35253893, 2022). "Given that mutations of ZMYM3 have been implicated in the pathogenesis of medulloblastoma, and intellectual disability syndromes, it will be interesting to establish whether the loss of this putative scaffolding ability plays a role in either of these pathologies." (PMID 30889214, 2019). "Somatic analysis of the disease-involved sample was consistent with non-WNT/non-SHH medulloblastoma, including ZMYM3 p.Ala217fs and SETD2 p.Glu1582Lys variants, in addition to copy number gain of chromosome 7, loss of chromosome 8 and 13, and isochromosome 17q." (PMID 36980535, 2023).
Cognitive impairment (3 papers, 2020 to 2025). Abnormal cognition is characterized by deficits in thinking, reasoning, or remembering. "We report a 19-year-old female with a de novo heterozygous variant in ZMYM3 (NM_201599.3:c.1927C>G, p.(His643Asp)), presenting with ADHD symptoms, poor motor coordination, and mild cognitive impairments." (PMID 40896224, 2025). "In conclusion, the ZMYM3 GA-STR is a prime example in which alleles at the extreme short and long ends of exceptionally long STRs may be associated with a spectrum of major human disorders in which cognition impairment is the predominant phenotype." (PMID 33173136, 2020). "In conclusion, we propose selective advantage for the exceptional length of the ZMYM3 GA-STR in human, and its link to a spectrum of diseases in which major cognition impairment is a predominant phenotype." (PMID 33173136, 2020).
male infertility (3 papers, 2017 to 2022). The inability of the male to effect fertilization of an ovum after a specified period of unprotected intercourse. "It has been reported that deficiency of the genes with similar expression profile, such as Zmym3, Ku70, Fam46d, Pdha2, Tex101 and Spata19, etc. always resulted in spermatogenic problems leading to male infertility, thus validating the essential roles of these genes." (PMID 29563520, 2018). "Knockout (KO) of Zmym3 in mice using the CRISPR-Cas9 system resulted in adult male infertility." (PMID 28661483, 2017).
chronic lymphocytic leukemia (2 papers, 2022 to 2024). "These auto-Abs were against ACAN, a known biomarker in RA and ZMYM3 and RNF111, implicated in chronic lymphocytic leukemia and cancers, respectively." (PMID 38470480, 2024).
hepatocellular carcinoma (2 papers, 2024 to 2026). A malignant tumor that arises from hepatocytes. "ZMYM3 promotes hepatocellular carcinoma metastasis by upregulating CTTN and inducing invadopodia formation." (PMID 41775697, 2026). "Additionally, we analyzed the clinical correlations of KDM1A expression level, ZMYM3 expression level, liver-TE-related gene expression profiles, and HNF4A downstream gene expression profiles in the TCGA and ICGC hepatocellular carcinoma expression profile datasets." (PMID 38965210, 2024).
Alzheimer disease (1 paper, 2020). A progressive, neurodegenerative disease characterized by loss of function and death of nerve cells in several areas of the brain leading to loss of cognitive function such as memory and language. "ZMYM3 was previously reported among the top three genes involved in the progression of late-onset Alzheimer’s disease." (PMID 33173136, 2020).
aortic stenosis (1 paper, 2014). Aortic valve stenosis is a aortic valve disease caused by the incomplete opening of the aortic valve. "One missense mutation (c.1321C > T) was identified in the candidate gene ZMYM3 in three affected males with a previously unrecognized syndrome characterized by unique facial features, aortic stenosis and hypospadia was detected." (PMID 24721225, 2014).
diabetes (1 paper, 2025). "Further, MFHAS1 and IQGAP2 have some known association with diabetes or related disorders, whereas the other three genes: ZMYM3, HSD17B10 and ABCB7 have no known direct association with diabetes." (PMID 41462339, 2025).
leukemia (1 paper, 2022). A malignant (clonal) hematologic disorder, involving hematopoietic stem cells and characterized by the presence of primitive or atypical myeloid or lymphoid cells in the bone marrow and the blood. "This difference is mainly found in proteins functionally related to each pathology, for example: sCD44, HIF1A, ZMYM3 or PTPRC for CSF + LM in lymphoma and S100A9, TRAF3, KLK3, KLK2, PTPRC, among others, in the case of CSF + LM in leukemia." (PMID 35053611, 2022).
liver cancer (1 paper, 2024). An epithelial or non-epithelial malignant neoplasm that arises from the liver. "Functionally, we found that knocking down ZMYM3 inhibits KDM1A-mediated growth of liver cancer cells." (PMID 38965210, 2024). "Functionally, knocking down ZMYM3 inhibits KDM1A-mediated growth of liver cancer cells." (PMID 38965210, 2024). "Our findings strongly suggest that ZMYM3 is necessary for the epigenetic regulatory role of KDM1A and is vital for KDM1A to exert its pro-growth effect in liver cancer cells." (PMID 38965210, 2024).
prion disease (1 paper, 2020). A transmissible disease that is caused by a protein that is able to induce abnormal folding of normal cellular proteins, leading to characteristic spongiform brain changes, which are associated with neuronal loss without an inflammatory response. "While GWAS approaches employ single nucleotide polymorphisms rather than STRs, and therefore can fail to detect instances of association with STRs, they have linked ZMYM3 to a number of neurological disorders of major cognitive impairment, including prion disease and multiple sclerosis." (PMID 33173136, 2020).
thymoma (1 paper, 2024). A neoplasm arising from the epithelial cells of the thymus. "Types A, AB, and B2 thymomas share many of these genes, with additional occurrences of PAX7 and CSF1R in Type A thymoma and ZMYM3 in Type AB thymoma." (PMID 38338833, 2024).
cancer (5 papers, 2022 to 2025). A tumor composed of atypical neoplastic, often pleomorphic cells that invade other tissues. "As mutations in ZMYM2 and ZMYM3 have been identified in several cancers, these results may reveal cancer-relevant functions of these poorly characterized ZnF proteins." (PMID 35253893, 2022). "Indeed, both ZMYM2 and ZMYM3 have been implicated in several human diseases including cancer." (PMID 35253893, 2022).
tumor (4 papers, 2016 to 2025). "Among the genes characterising the other larger subpopulation, ZMYM3 is a known tumor suppressor, whose deficiency impairs DNA repair by homologous recombination and can result in high genome instability." (PMID 35681161, 2022). "Loss-of-function mutations in the Lysine Demethylase 6A (KDM6A), Lysine Methyltransferase 2C (KMT2C), and Zinc Finger MYM-Type Containing 3 (ZMYM3) are enriched in Group 4 tumors, indicating convergent epigenomic dysregulation in tumor development." (PMID 40867227, 2025).
neurodevelopmental disorder (2 papers, 2024 to 2025). A behavioral and cognitive disorder with onset during the developmental period that involves impaired or aberrant development of intellectual, motor, or social functions. "Moreover, a very recent study reported ZMYM3 deleterious variants in an X-linked neurodevelopmental disorder (NDD), introducing ZMYM3 as a neurodevelopmental disorder (NDD) gene." (PMID 39119040, 2024).
ZMYM3 also shares sentences with these, for which no sentence is quoted: prostate carcinoma (2 papers); Aicardi–Goutières Syndrome (1); Allan-Herndon-Dudley syndrome (1); Ewing sarcoma (1); Infertility (1); intellectual disability syndromes (1); lung squamous cell carcinoma (1); lymphoma (1); melanoma (1); neurological disorders (1); pediatric cancers (1).